MIR640 (microRNA 640)
Synonyms: hsa-mir-640; MIRN640
Gene: MicroRNA gene on chromosome 19 (19,435,063 to 19,435,158, forward strand). Ensembl gene ENSG00000207821.
Gene Ontology:
Biological process: miRNA-mediated post-transcriptional gene silencing
Cellular component: RISC complex
Homologues: Orthologues: chimpanzee ptr-mir-640 (99% identical), macaque mml-mir-640 (97% identical).